SDC3 (syndecan 3)
Diseases named in the same sentence as SDC3 in open-access papers (continued):
Sharing a sentence is not in itself a finding about the gene and the disease.
pancreatic cancer (4 papers, 2017 to 2025). "Recently, SDC3 expression was associated with perineural invasion in pancreatic cancer." (PMID 34445387, 2021). "Upregulation of SDC3 contributes to perineural invasion and poor outcomes in pancreatic cancer." (PMID 37964984, 2023).
prostate carcinoma (4 papers, 2018 to 2025). A carcinoma that arises from epithelial cells of the prostate gland. "Nilton Jos é Santos found that patients with SDC3 immunostaining positive prostate cancer had a poor prognosis." (PMID 36482887, 2022). "Down-regulation of RPTPβ/ζ expression has been shown to initiate epithelial-tomesenchymal transition and to increase experimental prostate cancer metastasis in nude mice, while the effects of PTN in prostate cancer growth have been attributed to its interaction with syndecan-3." (PMID 30427932, 2018). "Notably, PTN’s interaction with SDC3 triggers the activation of ERK1/2, thereby facilitating the metastasis of prostate cancer cells." (PMID 39285301, 2024).
renal cell carcinoma (4 papers, 2020 to 2025). "Additionally, the high expression level of SDC3 was also associated with poor prognosis in patients with renal cell carcinoma." (PMID 33178362, 2020). "Another study showed that SDC3 regulated by the circSCARB1/miR-510-5p axis functioned as an oncogene in renal cell carcinoma." (PMID 33621194, 2021).
lung carcinoma (3 papers, 2008 to 2023). "Similarly, syndecan-2 was noted to promote focal adhesion formation in Lewis-lung carcinoma cells, and syndecan-2 and syndecan-3 induce filopodia formation in COS-1, CHO-K1, Swiss 3T3, and dendritic cells." (PMID 18545691, 2008).
neuroblastoma (3 papers, 2019 to 2020). Neuroblastoma (NB) is the most common solid, extracranial childhood tumor. "In neuroblastoma, it has been revealed that there existed an association between SDC3 expression and improved prognosis." (PMID 33178362, 2020). "It is worth noting that like neurons, SH-SY5Y neuroblastoma cells endogenously express SDC3 and colocalization of SDC3 with Aβ1–42 could be also demonstrated in the SH-SY5Y cell-line (MOC = 0.81 ± 0.39)." (PMID 30718543, 2019).
osteoarthritis (3 papers, 2014 to 2022). A noninflammatory degenerative joint disease occurring chiefly in older persons, characterized by degeneration of the articular cartilage, hypertrophy of bone at the margins and changes in the synovial membrane. "Finally, it has been shown that SDC3 is expressed by hypertrophic chondrocytes in growth plate and during osteoarthritis, however, its role is not known in these processes." (PMID 24516627, 2014).
Alzheimer disease (2 papers, 2022 to 2025). A progressive, neurodegenerative disease characterized by loss of function and death of nerve cells in several areas of the brain leading to loss of cognitive function such as memory and language. "Our study demonstrates that downregulation of SDC3 expression in 5×FAD mouse models can partially ameliorate Alzheimer’s disease-associated neuropathological alterations and cognitive impairments." (PMID 40564963, 2025).
brain neoplasm (2 papers, 2018 to 2022). A neoplasm (disease) that involves the brain. "This analysis identified neoplasms and nervous system diseases as the most associated diseases with the TRPV2 interactome, and highlighted a set of genes previously associated to brain neoplasms, such as: ABR, FGF1, KCNJ10, PEBP1, PLP1, SDC3 and TRPV2." (PMID 29719613, 2018).
channelopathy (2 papers, 2024 to 2025). Channelopathies are a group of diseases caused by the dysfunction of ion channel subunits or their interacting proteins. "Accordingly, excessively prolonged mechanotransduction under allostasis could bear relevance in the evolvement of Piezo2 channelopathy due to the altered cell surface charge of syndecan-3 by shedding or charge-atltering variants of the SDC3 gene." (PMID 38534336, 2024). "Even more importantly, the shedding or charge-altering variants of Syndecan-3 may contribute to the Piezo2 channelopathy-induced disruption of the Piezo2-initiated proton-based ultrafast long-range signaling through VGLUT1 and VGLUT2." (PMID 38534336, 2024). "Moreover, the charge-altering variants of syndecan-3-encoding SDC3 gene may have special relevance to the disruption of this crosstalk during the aging process, since Piezo2 channelopathy is theorized to be also subject to mitochondrial dysfunctionality." (PMID 38534336, 2024). "DOMS may interfere with this hippocampal theta rhythm synchronization due to acute Piezo2 channelopathy and functional syndecan-3 depletion." (PMID 38534336, 2024).
muscular dystrophies (2 papers, 2016 to 2018). "Loss of SDC3 in satellite cells prevents self‐renewal and rehoming of satellite cells to their niche, maintaining a pool of activated, proliferating cells that largely ameliorate muscular dystrophy in mdx mice." (PMID 30129974, 2018). "Manipulating syndecan-3 provides a promising target for development of therapies to enhance muscle regeneration in muscular dystrophies and in aged muscle." (PMID 27757223, 2016). "Sdc3−/− satellite cells do not appear exhausted in either dystrophic muscle or aged muscle apparently enhancing muscle regenerative capacity, identifying a new potential therapeutic target for the treatment and management of muscular dystrophies, repeated acute injuries and muscle aging." (PMID 27757223, 2016).
amyloid (1 paper, 2019). "Colocalization of amyloid plaques with members of the syndecan family of HSPGs, along with the increased expression of syndecan-3 and -4 have already been reported in postmortem AD brains." (PMID 30718543, 2019).
aneurysm (1 paper, 2025). Bulging or ballooning in an area of an artery secondary to arterial wall weakening. "It encompasses four components: syndecan-1, syndecan-2, and syndecan-4 (with syndecan-3 only expressed in neural tissue), which have a fundamental role in regulating the events of acute and chronic aorta damage subsequently correlated with the formation of aneurysms." (PMID 39940978, 2025).
benign breast disease (1 paper, 2013). "We first utilized ISH to determine the expression of GFRα1, GFRα3 and SDC3 mRNA in mammary tissue from benign breast disease (BBD) and MC." (PMID 23351331, 2013).
benign gynecological tumors (1 paper, 2021). "In our clinical specimens, the SDC3 expression was upregulated by approximately 2-fold in OvC tissues compared to both contralateral normal fallopian tube tissues and normal fallopian tube tissues from patients with benign gynecological tumors." (PMID 33621194, 2021).
breast tumor (1 paper, 2025). "Moreover, hypoxia-induced angiogenic HIF1α/VEGF-A signaling was related to SDC3 upregulation in hypoxic tumors, which further implicates SDC3 in breast tumor growth and vascular remodeling." (PMID 41148827, 2025). "Since a protein’s function is often closely tied to its precise location within tissues, cells, and subcellular structures, we suggest that the spatial distribution of SDC3 may be of relevance to breast tumor biology." (PMID 41148827, 2025). "In breast cancer metastasis, no significant alterations in SDC3 expression were detected, which might suggest that the molecule plays a distinct role in the early and late stages of breast tumor development." (PMID 41148827, 2025).
cocaine abuse (1 paper, 2017). Disorders related or resulting from use of cocaine. "The results indicated that, in addition to syndecan-3, other HS proteoglycans in the LH contribute to resilience to cocaine abuse." (PMID 29066725, 2017).
cocaine addiction (1 paper, 2019). "SDC3 null animals were more susceptible to cocaine addiction, a situation that could be reversed upon re-expression of SDC3." (PMID 31998313, 2019).
Cognitive impairment (1 paper, 2025). Abnormal cognition is characterized by deficits in thinking, reasoning, or remembering. "Together, these findings suggest that downregulation of the SDC3 gene partially mitigates cognitive impairments in 5×FAD mice, offering potential insights into the role of SDC3 in neurodegenerative disease progression." (PMID 40564963, 2025). "The rationale behind this experimental design is rooted in previous studies demonstrating that complete knockout of the SDC3 gene leads to cognitive impairment, which overlaps with the cognitive deficits observed in 5×FAD mice, thereby potentially confounding the experimental results." (PMID 40564963, 2025). "In contrast, SDC3 heterozygous mice did not exhibit significant cognitive impairment in behavioral tests, indicating that partial deletion of SDC3 does not directly affect cognitive function." (PMID 40564963, 2025).
colon cancer (1 paper, 2024). "SDC3 could also be a WNT2 receptor in colon cancer and a potential regulator for the development of chronic inflammation." (PMID 39228892, 2024). "HPV capsid proteins L1 and L2 may induce virus internalization, probably through the attachment to syndecan 3 (SDC3), a known HPV-binding receptor during colon tumorigenic processes and a common overregulated gene in colon cancer." (PMID 39228892, 2024).
colorectal cancer (1 paper, 2013). A primary or metastatic malignant neoplasm that affects the colon or rectum. "Degradation of RIP-generated intracellular domain fragments has been reported for other γ-secretase substrates such as Notch, syndecan-3, nectin-1α, p75, deleted in colorectal cancer (DCC) and members of the APP family." (PMID 24015300, 2013).
HIV-1 infection (1 paper, 2013). The type species of lentivirus and the etiologic agent of acquired immunodeficiency syndrome (AIDS). "However, these molecules may affect HIV-1 infection in an opposite way as some, such as mannose-binding lectin (MBL) and langerin, inhibit HIV-1 infection, while others, such as galectin-1, DC-SIGN, mannose receptor, syndecan-3 and DCIR, increase the susceptibility to HIV-1 infection." (PMID 24330394, 2013).
listeriosis (1 paper, 2020). A bacterial infection caused by Listeria monocytogenes. "This phenotype is not seen in Sdc3-/- or Sdc4-/- mice, indicating that ablation of Sdc1 causes a specific gain of function that enables mice to resist listeriosis." (PMID 32453780, 2020).
metastatic tumors (1 paper, 2021). "In addition, we also found a poor prognosis for patients with a high expression of SDC3 in primary and metastatic tumors from other studies." (PMID 34445387, 2021). "SDC3 gene overexpression showed prognostic value for reduced biochemical recurrence in the MSKCC dataset and overall survival for metastatic disease in the SU2C/PCF Dream Team dataset." (PMID 34445387, 2021).
myeloid leukemia (1 paper, 2020). A clonal proliferation of myeloid cells and their precursors in the bone marrow, peripheral blood, and spleen. "We should note that other syndecan family members may also contribute to myeloid leukemia, since knockdown of SDC2, SDC3, SDC4 either individually or in combination led to significant growth inhibition." (PMID 33243988, 2020).
myeloma (1 paper, 2012). "Expression of mRNA encoding syndecan-2 and -3 was only found in the myeloma cell lines U-266 and KMS-5, however the U-266 cells showed a low expression of syndecan-2 mRNA compared to KMS-5 and no expression of syndecan-3 mRNA." (PMID 22777011, 2012).
osteoporosis (1 paper, 2021). A condition of reduced bone mass, with decreased cortical thickness and a decrease in the number and size of the trabeculae of cancellous bone (but normal chemical composition), resulting in increased fracture incidence. "Deletion of Sdc3 leads to low bone volume, increased bone fragility, and increased bone marrow fat in young adult mice, a premature osteoporosis‐like phenotype." (PMID 33769615, 2021). "Thus, deletion of Sdc3 leads to a premature osteoporosis‐like phenotype characterized by not only low bone volume and fragility, but also increased BMAT, possibly due to a preferential switch from osteoblastogenesis to adipogenesis at a progenitor level." (PMID 33769615, 2021). "Thus, SDC3 may be a novel therapeutic target for anabolic drug development for prevention or treatment of osteoporosis." (PMID 33769615, 2021).
osteosarcoma (1 paper, 2022). A usually aggressive malignant bone-forming mesenchymal neoplasm, predominantly affecting adolescents and young adults. "We developed a new prognostic risk model for osteosarcoma based on 7 glycolytic genes (INSR, FAM162A, GLCE, ADH5, G6PD, SDC3, HS2ST1) by bioinformatics." (PMID 36387908, 2022). "A risk model based on seven glycolytic genes (INSR, FAM162A, GLCE, ADH5, G6PD, SDC3, HS2ST1) can effectively evaluate the prognosis of osteosarcoma, and in vitro experiments also confirmed the important role of INSR in promoting OS migration." (PMID 36387908, 2022).
ovarian serous cystadenocarcinoma (1 paper, 2022). A malignant serous cystic epithelial neoplasm arising from the ovary. "Analysis of RNASeq data revealed that SDC3 mRNA expression is significantly upregulated 3.5-fold in ovarian serous cystadenocarcinoma tissue (n = 374) compared with control tissue (n = 133) (p = 4.01 × 10−39)." (PMID 35628603, 2022).
ovarian tumor (1 paper, 2021). "The IHC assay result further confirmed that while the expression of SDC3 was high in the ovarian tumor tissues with lower expression of miR-138-5p, the expression of SDC3 was low in the ovarian tumor tissues with higher expression of miR-138-5p." (PMID 33621194, 2021).
pancreatic adenocarcinoma (1 paper, 2020). "Other tumor types with a significant correlation with the hypoxia signature were thymoma (THYM) and THCA for SDC3, and TGCT and pancreatic adenocarcinoma (PAAD) for SDC4." (PMID 33117401, 2020).
pancreatic ductal carcinoma (1 paper, 2022). "In pancreatic ductal carcinoma, Sdc3 expression correlates with primary tumor size in a mouse model." (PMID 35628603, 2022).
periodontitis (1 paper, 2019). An acute or chronic inflammatory process that affects the tissues that surround and support the teeth. "Syndecan-3 was detected in both patient groups, and significantly more was present in the sera of RA patients in comparison with those with periodontitis (P = 0.004)." (PMID 31300004, 2019). "RA levels of shed syndecan-3 are tenfold higher than in periodontitis." (PMID 31300004, 2019). "Finally, the results showed that shed syndecan-3 does occur in vivo in the human autoimmune/inflammatory conditions of RA and periodontitis." (PMID 31300004, 2019). "In periodontitis, the lower levels of syndecan-3 suggest other types of syndecans may be shed, reflecting different expression profiles between inflamed tissues." (PMID 31300004, 2019). "The median syndecan-3 level was 2219 pg/ml in RA and 220 pg/ml in periodontitis." (PMID 31300004, 2019).
preeclampsia (1 paper, 2025). Preeclampsia is a hypertensive disorder of pregnancy that is characterized by new-onset hypertension with proteinuria presenting after 20 weeks of gestation, and depending on mild or severe forms may initially present with severe headache, visual disturbances, and hyperreflexia. "Lastly, we found that the SLC9A9, SH2B3, SDC3, RCC2, F13A1, CCL2, and CBLB in macrophages were likely to be correlated with preeclampsia." (PMID 40216654, 2025). "Of all the immune cell-regulated preeclampsia differential genes SLC9A9, SH2B3, SDC3, RCC2, F13A1, CCL2, and CBLB were consistently expressed in two transcriptome datasets, and all were highly expressed in macrophages." (PMID 40216654, 2025).
psoriasis (1 paper, 2022). An autoimmune condition characterized by red, well-delineated plaques with silvery scales that are usually on the extensor surfaces and scalp. "Therefore, SDC3 has the possibility to be a crucial part in the pathogenesis of psoriasis and influence the therapeutic response in psoriasis." (PMID 36059983, 2022).
renal carcinoma (1 paper, 2025). A carcinoma arising from the epithelium of the renal parenchyma or the renal pelvis. "As SDC3 has been implicated in the progression of ovarian, pancreatic, and renal cancers, we sought to determine whether the molecule contributes to the aggressive behavior of breast cancer cells, and if it could serve as a biomarker for the disease." (PMID 41148827, 2025).
schizophrenia (1 paper, 2016). A major psychotic disorder characterized by abnormalities in the perception or expression of reality. "There are 4 genes, SOX9, HEPH, AQP1, and SDC3 as susceptible genes, and it was already reported that SDC3 has a weak association with schizophrenia in related GWAS." (PMID 27510319, 2016).
Sepsis (1 paper, 2022). Sepsis is defined as life-threatening organ dysfunction caused by a dysregulated host response to infection. "Circulating levels of soluble SDC1 and SDC3 have been reported to be increased during critical illnesses (including sepsis) compared with control patients." (PMID 34355516, 2022).
serous ovarian cancer (1 paper, 2021). "Although our study revealed the function of the TRPM2-AS/miR-138-5p/SDC3 axis in OvC tumorigenesis and cisplatin resistance, these findings might only be applicable for the pathogenesis of high-grade serous ovarian cancer (HGSC)." (PMID 33621194, 2021).
virus infection (1 paper, 2023). "Previous studies found that SDC3 plays an important role in inflammatory diseases and virus infection." (PMID 37047630, 2023). "For cells, SDC3 is expressed in many cell types, participates in the regulation of growth factor signal, cell adhesion and migration, and proliferation and differentiation, and also plays an important role in inflammation and virus infection." (PMID 37047630, 2023).